INS (insulin)
Diseases named in the same sentence as INS in open-access papers (continued):
Sharing a sentence is not in itself a finding about the gene and the disease.
Insulin resistance (continued). "In contrast to primary human adipocytes, Sfrp5 did not affect insulin signaling in hSkMC, neither under basal culture conditions nor following MCP-1-induced insulin resistance." (PMID 24465779, 2014). "Overall, however, there were 48% of children with IGT who did not exhibit elevations in fasting insulin, again suggesting a high prevalence of IGT unrelated to insulin resistance." (PMID 24755002, 2014). "A second group showed non-compensated insulin resistance (normoinsulinemic, BATIRKO N, fasted insulin plasma levels = 0.42 ± 0.05 ng/mL, p < 0.05 vs. BATIRKO MH), normal islet size (0.02 ± 0.008 islet area/pancreas area, ns." (PMID 25077985, 2014). "Although our work does not discount the possibility that ENPP1 contributes to insulin resistance, it does add another dimension that will have to be considered in future work exploring the influence ENPP1 has on liver insulin signalling." (PMID 25539584, 2014). "Because fasting glucose and insulin levels did not change after G-CSF treatment, we also suggest that enhanced UCP-1 expression in BAT after G-CSF treatment is a process independent of insulin resistance." (PMID 25144367, 2014). "In contrast with the reported beneficial effects of CPAP on glucose metabolism and insulin resistance in OSA patients, some studies demonstrated that CPAP treatment for 3 or 6 months did not improve fasting glucose or insulin plasma levels." (PMID 25400585, 2014). "The general mechanisms of IL-18 in the context of insulin resistance involve lineal effects of IL-18 on insulin signaling with or without tumor necrosis factor-α (TNF-α) stimulation in tissues and a secondary response of IL-18 to insulin resistance." (PMID 24282409, 2013). "Its level did not correlate with markers of insulin resistance (HOMA-IR), insulin sensitivity (HOMA-S%), pancreatic beta-cell function (HOMA-B%) and insulin sensitivity in dynamic conditions (OGIS)." (PMID 24083682, 2013). "Beside its direct negative interference with the insulin signaling pathway, TNF-α also indirectly induces insulin resistance by altering adipocyte differentiation and adipocyte lipid metabolism." (PMID 24455420, 2013). "Our previous studies with homozygous C3H-11NSY mice demonstrated that impaired insulin secretion in NSY mice was accounted for mostly by Chr11 and that insulin resistance, which is independent of adiposity and obesity, was accounted for partly by Chr11." (PMID 23671880, 2013). "A study in Turkey evaluated insulin resistance in ERT patients with GD and without overweight (n=14), and showed that they had higher levels of fasting insulin, post-load glucose and insulin when compared to controls." (PMID 23570288, 2013). "Plasma levels of insulin and HOMA-IR, but not plasma glucose levels, were increased in the continuous group at week 17, reflecting GC-induced insulin resistance." (PMID 23717502, 2013). "The hyperinsulinemia is not just a consequence of insulin resistance, because BPA directly regulates pancreatic insulin content and insulin release in isolated islet of Langerhans from the mouse." (PMID 22347437, 2012). "Further, only male mice on HFD showed impaired insulin tolerance 30 and 60 minutes after an ITT compared to all other groups, consistent with established insulin resistance in male but not female mice." (PMID 23049932, 2012). "Research into insulin resistance, type 2 diabetes and the metabolic syndrome took off in the 1960s after the first human plasma insulin assays demonstrated that the majority of cases of late-onset diabetes could not be explained sufficiently by lack of insulin." (PMID 22643933, 2012). "On the contrary, mice lacking Gpx1 were protected from high-fat diet-induced insulin resistance, while administration of NAC rendered them more insulin-resistant and increased fasting glucose levels in the blood." (PMID 23730255, 2012). "Insulin normally inhibits HGP, however this suppression is not well achieved in subjects with hepatic insulin resistance." (PMID 22947097, 2012).
Insulin resistance (continued). "Unfortunately, as we did not measure fasting glucose or fasting insulin, we were unable to determine HOMA-IR as a direct marker for insulin resistance." (PMID 22831708, 2012). "Although OP rats did not develop insulin resistance, the lowering of plasma GIP by all dietary levels of RS was considerable and deserves further investigation in animal models with impaired insulin sensitivity." (PMID 23098187, 2012). "Since adipose tissue, muscle and liver are key players in systemic insulin resistance, this data suggests that ASP, independently of its adiposity effects, influences insulin sensitivity in the absence of diet induced-obesity." (PMID 23056509, 2012). "They showed no insulin resistance (HOMA-IR = 1), normal to moderately increased insulin sensitivity (Matsuda and Cederholm index), but decreased β–cell response to glucose uptake." (PMID 21738662, 2011). "Although the plasma insulin concentration did not change significantly, an HOMA-IR index significantly decreased, suggesting a decrease in insulin resistance or decreased glucose concentration following flaxseed supplementation." (PMID 21554710, 2011). "The findings suggest that men with metabolic complications that include peripheral insulin resistance, with or without well-controlled HIV infection, have altered myocardial glucose utilization per unit insulin and left ventricular relaxation." (PMID 22151886, 2011). "Another limitation relates to the indices of insulin resistance, HOMA-IR and QUICKI, which are not as accurate as the euglycemic-hyperinsulinemic clamp or FSIGT to measure insulin sensitivity/resistance." (PMID 22196129, 2011). "Furthermore, no validation tests for the use of any surrogate measures of insulin resistance in Saudi subjects using euglycemic clamp have ever been conducted, and it is not known whether they are able to identify insulin-resistant subjects using cut-off points published for other populations." (PMID 20622341, 2010). "In terms of research on insulin resistance, cell culture work is lacking, however animal studies tend to support a beneficial role of ALA on insulin sensitivity." (PMID 19664246, 2009). "Conversely, mice lacking the RBP4 gene show increased insulin sensitivity, and normalizing increased RBP4 serum levels improves insulin resistance and glucose intolerance." (PMID 19460132, 2009). "Although higher insulin levels were found in DTC patients, the related exogenous hyperthyroxinemia did not induce the insulin resistance reported by some but not all authors with regard to overt endogenous hyperthyroxinemia." (PMID 19014658, 2008). "Interestingly, a similar lack of response to insulin was also observed in type 2 diabetes patients and following insulin resistance induced by lipid infusion, indicating that this phenomenon may indeed be related to insulin resistance." (PMID 19011679, 2008). "The insulin clamp tests performed 10 to 11 weeks after EV injection, when typical PCO are fully developed, showed no insulin resistance in the PCO group." (PMID 16146570, 2005). "Although this association has been explored, most previous studies have relied on indirect surrogate markers of insulin activity, such as fasting glucose levels or the homeostatic model assessment of insulin resistance (HOMA-IR), rather than directly measured fasting insulin levels." (PMID 41464556, 2025). "Insulin resistance and sensitivity were not measured, since these women were diagnosed with T2DM previous to the study, and there is evidence that alterations in HRV are mediated by hyperglycemia rather than insulin." (PMID 40267043, 2025). "In a low-dose DHT mouse model of nonobese PCOS, skeletal muscle actually showed elevations in insulin-stimulated glucose transport, AKT phosphorylation and GLUT4 protein levels, unlike the molecular insulin resistance observed in the livers and white adipose tissue of these mice." (PMID 40013621, 2025).
Insulin resistance (continued). "In aged adiponectin knockout mice, the chronic absence of adiponectin leads to insulin resistance in the hippocampus, characterized by the decreased phosphorylation of AMPK, Akt, and PI3K, despite normal insulin plasma levels and insulin receptor expression in the hippocampus." (PMID 40717739, 2025). "As changes in PM2.5‐induced cardiovascular insulin resistance have not yet been examined in female mice, we tested whether a 30‐day CAP exposure impacts cardiac insulin sensitivity." (PMID 40892707, 2025). "The metabolic score for insulin resistance (METS-IR), a non-insulin-based index derived from fasting blood glucose, triglycerides, high-density lipoprotein cholesterol, and body mass index, offers a practical surrogate for assessing insulin sensitivity." (PMID 41180178, 2025). "Although fasting insulin levels provide significant insight into the metabolic status of pregnant women, the lack of fasting blood glucose measures to calculate HOMA-IR or the lack of other dynamic measures of insulin resistance is a limitation of our study." (PMID 40646607, 2025). "However, unlike IL-6, TNF-α can only increase insulin resistance by inhibiting AMPK signaling pathway and decreasing glucose uptake, impairing insulin signaling and lipid metabolism." (PMID 41515940, 2025). "While induction of lipolysis over two days using PDE inhibition—either with IBMX or a combination of PDE3 and PDE4 inhibitors—did not lead to significant insulin resistance, our data suggest that PAK inhibition modulates insulin signaling mainly independently of its role in regulating lipolysis." (PMID 40659091, 2025). "The failure of dasatinib in palmitic acid-induced insulin-resistant cells could perhaps allude to the lack of functional PI3/AKT pathway in this model, as this is a well-established in vitro insulin resistance model." (PMID 41155560, 2025). "In females, blood glucose concentrations during the insulin tolerance test were not significantly modified between the groups, which is consistent with a previous study showing female mice are protected from HFD‐induced insulin resistance." (PMID 40108792, 2025). "Although this might suggest increased lipid mobilization without concurrent hepatic or peripheral insulin resistance, markers of lipolysis (ATGL and HSL) and key components of the insulin signaling cascade (Akt and AS160) were unchanged in adipose tissue." (PMID 41156477, 2025). "In contrast, the untreated db/db model diabetic mice showed no significant decrease in blood glucose levels post-insulin injection, with AUC values significantly higher than those of the C57BL/6J group, approximately 5.6 times greater, indicating marked insulin resistance." (PMID 40430283, 2025). "Importantly, the heightened expression of insulin-specific CD8 T cells in the high-H group was independent of BMIp, suggesting a specific relationship with insulin resistance." (PMID 39656436, 2025). "SCFAs also increase insulin levels (via GSIS) independent of blood glucose concentrations, and increase muscular and systemic insulin sensitivity, and obesity-related reductions in SCFAs promote peripheral insulin resistance and consequently hyperinsulinemia." (PMID 40696355, 2025). "While T1DM is characterized by a complete lack of insulin due to autoimmune destruction of pancreatic beta cells, T2DM is a multifactorial disorder with later onset, defined by insulin resistance and progressive beta cell failure, leading to a gradual decrease in insulin secretion." (PMID 39736865, 2024). "In a case-control study measuring inflammatory proteins in women with PCOS versus healthy controls, patients with insulin resistance were found to have elevated fasting levels of C3, C3a, and C5/5a, while PCOS patients who were insulin sensitive did not have elevated levels." (PMID 39610634, 2024).
Insulin resistance (continued). "Interestingly, these diet-specific changes in glucose and insulin were not supported by differential changes between diets in HOMA-IR, an indicator of insulin resistance." (PMID 39125421, 2024). "Notably, when insulin transport into the ARH was impaired by ablating insulin receptors in tanycytes, mice exhibited insulin resistance without changes in glucose tolerance." (PMID 39047908, 2024). "Although our study demonstrated the relationship between the severity of OSA and insulin resistance, evidence on whether positive airway pressure therapy for OSA improves insulin resistance has not yet been established." (PMID 38892846, 2024). "The pathophysiology of GDM involves β-cell dysfunction and insulin resistance during pregnancy but this study did not measure insulin; consequently, indicators relevant to MUAC and insulin resistance were not evaluated, and the mechanism was not discussed in depth." (PMID 38965475, 2024). "Furthermore, the SHBG levels in our study negatively correlated with the measures of insulin resistance – HOMA-R and serum insulin – both in healthy men and in non-diabetic men on chronic hemodialysis." (PMID 39014506, 2024). "Glucose disposal in the postabsorptive state is known to be less dependent on insulin and therefore, excessive postabsorptive HGP, rather than peripheral insulin resistance, may account for the hyperglycemia in ZDF rats." (PMID 38265288, 2024). "While indicators of mitochondrial biogenesis were reduced in insulin-resistant cells treated with supraphysiological levels of BCAA, BCAA did not alter indicators of mitochondrial dynamics regardless of the presence of insulin resistance." (PMID 39057712, 2024). "Although we did not see a significant difference in fasting blood insulin concentration among these three groups, the results of HOMA-IR, which is regarded as an index of insulin resistance, did show a significant difference between the ADRQβ-004 vaccine group and the HFD + L-NAME group (P = 0.025)." (PMID 36656412, 2024). "Notably, insulin levels were not increased in HFSD-fed vehicle-treated mice compared to LFD-fed mice despite HFSD-induced hyperglycemia and insulin resistance (see Section 3.4), suggesting that HFSD-fed mice had impaired β-cell function." (PMID 39195275, 2024). "The present study measured only serum insulin levels and HOMA-IR for assessing insulin resistance, which might not be completely accurate." (PMID 38892554, 2024). "Although euglycemic insulin clamp studies (clamp study) have not been performed in the PCOS population, a short-term, small, clamp study involving 10 patients with type 2 diabetes (T2DM) and obesity showed that insulin resistance improved on a KD." (PMID 39328462, 2024). "Likewise, 4 weeks of insulin treatment did not affect HFD-induced upregulation of SA-β-gal activity in gWAT, body weight or gWAT weight, although glucose intolerance and insulin resistance were significantly improved compared with the control HFD group." (PMID 38816549, 2024). "We showed that AT-IR (a product of fasting insulin and fasting free fatty acid [FFA]) may be useful in assessing adipose insulin resistance even in women without diabetes and obesity." (PMID 39013950, 2024). "Furthermore, evidence for the specific tissue sources of insulin resistance have previously been reported, with HOMA-IR reflecting hepatic insulin resistance and Matsuda Index reflecting whole-body insulin sensitivity; however, there is not full agreement." (PMID 37914981, 2024). "However, non-esterified fatty acids (NEFAs) are critical for normal insulin release, high levels of the formation of NEFA by a lipid infusion-induced pancreatic β-cell dysfunction and insulin resistance in T2DM." (PMID 38672494, 2024). "Fasting insulin resistance was not affected by the dietary interventions, probably due to the not excessively high values of HOMA-IR and the stable treatment with glucose-lowering drugs affecting insulin sensitivity, such as metformin." (PMID 38337618, 2024).
Insulin resistance (continued). "Considering that this study included only single-arm trials and did not analyze the homeostasis assessment of insulin resistance test (HOMA-IR), it is difficult to make inferences with certainty about an “insulin-sensitizing” advantage of KDs in relation to other diets." (PMID 37513538, 2023). "Our results could be interpreted to suggest that insulin resistance, rather than ANP, is related to fat distribution, and that the elevated insulin that accompanies insulin resistance leads to a reduction in ANP." (PMID 36905117, 2023). "The comparison of the effects of MOJ intake in women with or without insulin resistance showed the beneficial effects of MOJ on the cardiometabolic disorder including reduced levels of glucose, insulin, and HOMA-IR, as well as greater reduction of SBP and DBP in the insulin-resistant women." (PMID 37469434, 2023). "Because FGF21 can reduce insulin resistance, there is also an interesting study that does not focus on how FGF21 alleviates insulin signaling pathways but instead focuses upstream to modify FGF21 and construct FGF21 analogs through protein engineering to enhance its functionality and perdurability." (PMID 38069273, 2023). "Diacerein can reduce the HbA1c level without affecting the homeostasis model assessment-insulin resistance (HOMA-IR), indicating that it may play a role in insulin secretion." (PMID 36936906, 2023). "However, there were no considerable differences in levels of insulin, HOMA-IR (homeostatic model assessment for insulin resistance), or blood lipids between the SGA and AGA groups." (PMID 38004175, 2023). "Therefore, we wanted to verify the presence of CNS insulin resistance, via ICV delivery of S961, did not affect the distribution of IN insulin." (PMID 37076875, 2023). "Rats lacking melatonin showed marked glucose intolerance and insulin resistance, which may result from a widespread reduction in glucose transporter-4 (GLUT-4) in many insulin-targeted adipose tissues, such as adipose and hepatic cells." (PMID 36974476, 2023). "Interestingly, in the context of insulin resistance, when the metabolic signals such as PI3K signaling is inhibited, the mitogenic signals like the Ras-Raf-MAPK pathway of insulin are not interrupted and are possibly upregulated." (PMID 37664840, 2023). "Furthermore, while inhibition of nSMase2 with GW4869 prevents PAL-induced insulin resistance, the overexpression of wild type nSMase2 but not palmitoylation-defective mutant protein potentiates the suppressive effect of PAL on insulin signaling." (PMID 37640282, 2023). "Some studies suggest that increased BCAA levels may contribute to insulin resistance via the mTORC1 signaling pathway; however, other studies suggest that BCAA supplementation alone is unlikely to impair insulin sensitivity." (PMID 36765884, 2023). "Furthermore, p27−/− HFD mice displayed severe insulin resistance when compared to the WT HFD mice, suggesting that the lack of p27 interferes with insulin signalling in the context of obesity." (PMID 36768986, 2023). "However, in our large cohort covering a wide BMI range and precisely derived insulin sensitivity measures in an OGTT, we do not see a major role of the AcG/UnG ratio contributing to insulin resistance in the metabolic syndrome." (PMID 37420007, 2023). "FGF21 treatment did not significantly alter changes in insulin resistance, and the change in HOMA-IR between the groups was not significantly different following the treatment period (p = 0.88), consistent with both insulin and glucose." (PMID 36756310, 2023). "Indeed, this study showed that MB in both the presence and absence of diet intervention resulted in the reduction of insulin concentrations which was further evidenced by the decrease in HOMAR-IR index, hence, suggesting an attenuation in insulin resistance." (PMID 38096150, 2023).